S100B (S100 calcium binding protein B)
Diseases named in the same sentence as S100B in open-access papers (continued):
Sharing a sentence is not in itself a finding about the gene and the disease.
melanoma (continued). "One patient with CNS irAE was S100B positive and had S100B producing melanoma metastases in brain, muscle, subcutaneously, liver and lungs." (PMID 38171113, 2024). "Since its discovery in the 1980s, the expression of S100B has been used as a prognostic marker for malignant melanoma." (PMID 38892279, 2024). "S100B is currently one of the best characterized biomarkers of melanoma and has been routinely used as an immunohistochemical marker for diagnosis of malignant melanoma." (PMID 39156972, 2024). "Increasing levels of S100B correlate with disease progression, and levels of S100B are significantly higher in patients with stage IV melanoma than individuals with early-stage disease." (PMID 39156972, 2024). "The pro‐tumoral activity of S100B is also carried out in early‐stage melanoma through downregulation of IL‐6 signaling and subsequent suppression of anti‐tumoral immunity." (PMID 38775220, 2024). "The aim was to identify early‐stage melanoma patients at high risk of recurrence using liquid biopsy, estimating of mutated BRAF ctDNA and the level of tumor marker S100B in plasma." (PMID 39387479, 2024). "For several decades, the tumor marker S100B has been used to determine the prognosis of patients with advanced melanoma with ambiguous benefit." (PMID 39387479, 2024). "When comparing the S-100B (a common biomarker for melanoma activity) levels, we found very low values for samples 13 and 14, which correspond to the values found using CRISPRdx." (PMID 39644903, 2024). "One major strength is that S100B was measured at least monthly in all patients with melanoma, as it is both a melanoma marker and a brain damage marker." (PMID 38171113, 2024). "Data analyses of the whole group showed that 30.11% and 35.22% of melanoma patients expressed positive values for S100B and MIA, respectively." (PMID 37373887, 2023). "A rational follow-up of the present study is aimed at determining the efficacy and persistence of the DK/CRISPR toolbox in other human and murine melanoma lines having high levels of S100b." (PMID 36899866, 2023). "In melanoma patients, elevated serum S100B levels result from the cell death and protein degradation caused by apoptosis or necrosis." (PMID 38202181, 2023). "Serum S100B is considered a suitable marker for melanoma recurrence, and several studies and reviews have been published on the prognostic effect of serum S100B." (PMID 37664072, 2023). "A strong correlation between S100B expression in melanoma tumour tissue samples and tumour stage has been found." (PMID 37664072, 2023). "Targeted suppression of S100b therefore offers a therapeutic vulnerability to overcome drug resistance in melanoma." (PMID 36899866, 2023). "This study evaluated the association between biomarkers (S-100B, LDH) in stage IV melanoma and PET-derived indicators SUVmean/max, metabolically active tumor volume (MATV), and TLG." (PMID 36818450, 2023). "Thereafter, pentamidine has been used in S100B-targeted treatment of melanoma and S100B inhibition experiments in the pathological intestine and brain in vivo." (PMID 37508531, 2023). "One of the most investigated and useful biomarkers in melanoma is S100B, which belongs to the large family of S100 proteins, consisting of numerous isoforms, with more than 25 members sharing structural similarity and functional discrepancy." (PMID 37373887, 2023).
melanoma (continued). "In contrast, when extracellularly secreted via the receptor for advanced glycation end products (RAGE) signal transduction pathway, S100B facilitates tumor development in a mouse model of melanoma." (PMID 36899866, 2023). "Melanoma-associated antigens (MAAs), microRNAs (miRNAs), S100B, CRP, LDH, and circulating tumor cells (CTCs) are possible biomarkers for the diagnosis of melanoma." (PMID 37292567, 2023). "S-100B is produced by Schwann cells (a type of nerve cell) and has been found to be elevated in some cases of melanoma and other types of cancer." (PMID 37504268, 2023). "According to these observations, the measurement of serum S100B in the follow-up of patients with melanoma is a valuable tool for detecting disease progression in asymptomatic individuals." (PMID 38202181, 2023). "In melanoma, intracellular S100B interacts with proteins of different signaling pathways, such that S100B activates the glycolytic enzyme fructose 1,6-biphosphate (aldolase) and increases metabolism of melanoma cells." (PMID 36899866, 2023). "Serum S100B is also a marker of brain injury, and there is a high chance that serum S100B levels are elevated in melanoma patients with central nervous system metastases." (PMID 37664072, 2023). "In fact, the first study comparing S100B and different imaging techniques for predicting a melanoma relapse was conducted in 2006 involving a total of 192 melanoma patients." (PMID 38202181, 2023). "For example, S100B is a protein that is normally found in the brain, but it can also be produced by certain types of cancer, such as melanoma and glioma." (PMID 36979464, 2023). "Mouse B16 melanoma cells have been used for expressing differential levels of S100b under different pathological conditions in conjunction with tumor development." (PMID 36899866, 2023). "In a 2021 meta-analysis, the prognostic (predicting survival) and diagnostic (predicting relapse) significance of serum S100B and serum LDH in patients with melanoma was compared." (PMID 38202181, 2023). "Even if the value of S100-β as a prognostic marker in melanoma is low, there is still a correlation with the patient’s tumor burden and thus an association with overall survival of tumor-bearing metastatic melanoma patients." (PMID 36607507, 2023). "Similar to prostate cancer, there are commercially available tumor markers in melanoma patients such as S100β, LDH, the protein “melanoma inhibitory activity” (MIA), CRO, PD-L1, IL-8, TIL, osteopontin, and YKL-40." (PMID 36607507, 2023). "Overexpression of S100B is routinely used for disease-staging and for determining prognostic outcomes in patients with malignant melanoma." (PMID 36899866, 2023). "The less significant fraction of S100B, referred to as an extracranial fraction, is present in striated muscle cells, heart, kidneys, and malignant melanoma cells." (PMID 38138951, 2023). "Among the cases with a triple positive expression of tissue proteins, 11.53% (3/26) continued to overexpress serum S100B after surgery, reflecting the possibility of the occult presence of melanoma cells as a source of S100B protein." (PMID 37373887, 2023). "In histopathology, S100B is an established immunohistochemical marker of choice for malignant melanoma." (PMID 36235175, 2022). "In this work, a simple electrochemical immunosensor based on a chitosan/reduced graphene oxide (CS–rGO) nanocomposite was developed for sensitive determination of an S-100B protein, a tumor marker of malignant melanoma." (PMID 36199606, 2022).
melanoma (continued). "High levels of S100B are characteristic of Down Syndrome, Alzheimer’s disease, Creutzfeldt–Jakob disease, schizophrenia, multiple sclerosis, brain tumors, epilepsy, melanoma, myocardial infarction, muscle disorders, and sarcopenia." (PMID 35625541, 2022). "In melanoma, serum S100B concentration was positively correlated with tumour stage and negatively correlated with survival rate." (PMID 35785160, 2022). "The upregulated HOXC11 is also a transcription factor, regulating the expression of linage marker S100b in melanoma." (PMID 35269844, 2022). "In clinical practice, tests are available that allow the determination of the S100B protein, the presence of which in the serum is a marker of melanoma, useful in the diagnosis, prognosis, and treatment monitoring." (PMID 36235175, 2022). "Compared to the abundantly distributed and unspecific circulating protein CRP and cytosolic enzyme LDH, the cytoplasmic protein S-100B is considered as a more specific and reliable marker for malignant melanoma." (PMID 35494048, 2022). "Overexpression of S100B occurs in Down Syndrome, Alzheimer’s disease, Creutzfeldt–Jakob disease, schizophrenia, multiple sclerosis, brain tumors, epilepsy, melanoma, myocardial infarction, muscle disorders, and sarcopenia." (PMID 35625541, 2022). "Antibodies against CD3, CD20, and HMB45 plus S100B were used for VM and used to segment the ROI in B cells (CD20), T cells (CD3), and melanoma cells (PMEL/S100B), and the tumors were categorized into tumors with and without TLS." (PMID 35847846, 2022). "S100B is an important member of the S100 family that is aberrantly expressed in various malignant tumors, including melanoma, breast cancer, colon cancer, metastatic lung cancer and ovarian cancer." (PMID 35368338, 2022). "S100B is a clinical marker of melanoma progression and metastasis useful in serological monitoring of systemic therapy." (PMID 36235175, 2022). "Melanomas are visualized in FFPE tissue slides with antibodies such as S100B, PMEL17, and HMB45 (anti-PMEL17/gp100)." (PMID 35847846, 2022). "High S100B absorptions continue to be used as a biomarker for malignant melanoma, with the increasing amount of S100B indicating cancer progression." (PMID 36613714, 2022). "S100B(ββ) is also a clinically validated marker for malignant melanoma (elevated only in tumours), traumatic brain injury (TBI) and has been associated with cancer progression in multiple myeloma, NSCLC/SCLC and pancreatic cancer." (PMID 33573254, 2021). "Specifically, it was found that elevated S100B in malignant melanoma cells blocks CREB phosphorylation and inhibits IL6/STAT3-signaling." (PMID 34411141, 2021). "Melanoma-A consisted of CD63, PMEL, and S1000A1, while Melanoma-B consisted of S100B, FTH1, and AEBP1 expression." (PMID 33535416, 2021). "To date, S100B protein is currently mainly used as an immunohistochemistry marker to confirm melanoma diagnosis in pathological specimens." (PMID 33925387, 2021). "Taken together, the data with WM115, WM793, WM1158, SK-MEL-28 melanoma cell lines support the conclusion that elevated S100B negatively regulates IL6 expression and its downstream signaling as measured via phosphorylation of STAT3." (PMID 34411141, 2021). "Unfortunately, the blood concentration of S100B can be affected by several factors such as multiple trauma, skin colour, presence of melanomas, and its clinical utility is limited by the short half-life (3 hours) of S100B in blood." (PMID 33632753, 2021).
melanoma (continued). "In this study, we report that an analogue (complex 1) from the reported CRAF library suppresses melanoma cell proliferation and melanoma tumour growth in murine models of melanoma via blocking the S100B and RAF pathways." (PMID 33377602, 2021). "It is important to define a mechanism for how elevated S100B in malignant melanoma suppresses the IL6/STAT3 pathway." (PMID 34411141, 2021). "These genes are distinct from S100B, which is used in the diagnosis of melanoma by immunohistochemistry." (PMID 35008167, 2021). "Elevated S100B expression is a clinical biomarker of malignant melanoma (MM) indicating advanced disease stage, poor therapeutic response, and low patient survival." (PMID 33450915, 2021). "In summary, the combination of NMR and computational approaches provided insight into how S100A1 versus S100B bind small molecules specifically, which will enable improved drug design efforts to inhibit elevated S100B in melanoma." (PMID 33450915, 2021). "S100B is also located extracerebrally, such as in chondrocytes, Schwann cells, adipocytes and malignant melanoma cells, which influences S100B serum levels." (PMID 33670976, 2021). "Increased S100B protein expression has been observed in 74%–100% of patients with stage IV melanoma." (PMID 35003391, 2021). "An elevated S100B level is detected not only in psychiatric conditions but also in many other neurological disorders such as traumatic brain injury, malignant melanoma, amyotrophic lateral sclerosis, and subarachnoid hemorrhage." (PMID 34099858, 2021). "These small molecule fragments now provide a basis for designing next stage S100 inhibitors, including for targeting S100B in melanoma in cancer." (PMID 33450915, 2021). "The data presented here are also fully consistent with a mechanism reported earlier in which high S100B levels found in malignant melanoma bind to RSK, block its phosphorylation at T573, and sequester this enzyme to the cytoplasm." (PMID 34411141, 2021). "Using this approach, we observed that ~7% of the identified MelanA+/S100B+ melanoma cells were also positive for HLA-DR (13497 HLA-DR+ vs 177829 HLA-DR- cells)." (PMID 33842341, 2021). "As a result, it is proposed that phosphorylation of CREB in the nucleus is blocked by S100B-RSK complex, and CREB-dependent transcription of IL6 is inhibited, leading to the loss of IL6/STAT3 signaling in melanoma." (PMID 34411141, 2021). "In the COX models, we recruited two known prognostic biomarkers of melanoma, S100B, and WNT5A, to better identify the prognostic value of the hub genes." (PMID 32934956, 2020). "Within the MELmiR-7 panel, some miRNAs were identified as being able to discriminate different melanoma stages with a better diagnostic score than the currently applied serological tests based on LDH and S100B, and with high sensitivity and specificity." (PMID 32013263, 2020). "Apart from its use in clinical staging, S100B protein levels are widely used in the clinical management of melanoma patients to determine therapeutic responses." (PMID 33256110, 2020). "The levels of MIA and S100B were significantly higher in melanoma patients in comparison to HD and NED patients." (PMID 32709086, 2020). "S100B protein is another circulating serum factor with prognostic value for melanoma patients as its concentration reflects the response to treatment or tumor growth related to progression." (PMID 32992737, 2020). "Our data also demonstrated that the RAGE/S100B axis was involved in melanoma development and growth." (PMID 33256110, 2020).
melanoma (continued). "The concentration of circulating S100B predicts the duration of survival in melanoma patients and are very sensitive for the detection of metastatic growth of malignant melanoma, particularly at stage IV of the disease." (PMID 33299138, 2020). "Serum S100B level was reported as a prognostic marker for response to pembrolizumab and combined nivolumab and ipilimumab therapy in melanoma patients." (PMID 32992737, 2020). "S100B also appears to be a promising biomarker for treatment response and overall survival in melanoma patients treated with immune checkpoints inhibitors (anti PD-1 antibodies)." (PMID 33256110, 2020). "S100B expression is increased in melanoma cells compared with melanocytes, and can be used for the staging of metastatic malignant melanoma by immunohistochemistry." (PMID 32295074, 2020). "A recent study showed lower S100B levels from patients with stages I and II (primary melanoma) than stage III (regional melanoma) and stage IV (metastatic melanoma), the levels of S100B being the highest in patients with metastatic melanoma." (PMID 33256110, 2020). "In our earlier study, we observed that RAGE overexpressing WM115 melanoma cells also overexpressed S100B, when compared to control WM115 cells." (PMID 33256110, 2020). "Consistently, immunostaining for HMB45 and S‐100B further confirmed that primary melanoma was completely ablated by CAH‐mediated PDT therapy, whereas the remaining uncured mice exhibited varying degrees of tumor progression." (PMID 30886812, 2019). "In the present study, we primarily aimed to assess the added value of the biomarker S‐100B as a selection tool before FDG PET/CT scanning for the detection of recurrent disease in stage III melanoma patients." (PMID 31468535, 2019). "Both epidermal and dermal Tomato+ cells expressed melanocyte/melanoma markers S100b, Dct, MITF and Sox10." (PMID 31685822, 2019). "Thirteen patients were asymptomatic but had elevated S‐100B levels (in 54% recurrent melanoma on PET/CT)." (PMID 31468535, 2019). "The present study evaluated the tumor marker S‐100B in stage III melanoma patients as an additional tool to guide FDG PET/CT scanning for the detection of recurrent disease." (PMID 31468535, 2019). "These epidermal Mcs, not observed in control mice, also expressed the melanocyte/melanoma markers S100b, Dct, microphthalmia transcription factor (MITF) and Sox10." (PMID 31685822, 2019). "Immunofluorescence analysis of S100A8/A9 expression in tissue sections of primary melanomas revealed an exclusive and abundant expression of S100A8/A9 in cells of the TME, mainly granulocytes, whereas S100B expression was restricted to melanoma cells." (PMID 31806053, 2019). "In contrast to S100A8/A9, gene expression of the melanoma biomarker S100B was upregulated not only in melanoma metastases, but also in primary melanomas and in melanocytic nevi." (PMID 31806053, 2019). "S100B expression is increased in melanoma cells compared with melanocytes and can be used for the diagnosis of metastatic malignant melanoma by immunohistochemistry." (PMID 31330795, 2019). "The combination of three antibodies, anti-Melan A, -S100β and -Gp100 detected all melanoma cell lines well and showed negligible interaction with PBMCs." (PMID 30735560, 2019).